APOBEC3A (apolipoprotein B mRNA editing enzyme catalytic subunit 3A)
Diseases named in the same sentence as APOBEC3A in open-access papers (continued):
Sharing a sentence is not in itself a finding about the gene and the disease.
cancer (114 papers, 2012 to 2026). A tumor composed of atypical neoplastic, often pleomorphic cells that invade other tissues. "APOBEC3A (A3A), an enzyme that generates mutations across various cancers, has been proposed as a mediator of tumor heterogeneity and disease progression." (PMID 40059825, 2025). "Our findings provide new insight into the transcriptional control of APOBEC3A gene expression in squamous epithelia and provide a potential mechanism for the acquisition of APOBEC3A-induced mutations in cancer." (PMID 39548236, 2025). "APOBEC3A’s requirement in ribosome biogenesis strengthens its connection to cancer pathogenesis beyond its role in producing mutations across the genome." (PMID 38976757, 2024). "By modeling SMC5/6 loss in cancer cell lines, we found that APOBEC3A activity elicited high levels of DNA breaks leading to genotoxic cell death." (PMID 38886582, 2024). "Lastly, increasing the likelihood that our reproducible results are from APOBEC3A’s function on RNA, in cultured cancer cell lines, APOBEC3A associated genomic mutation rates are variable and episodic in nature over lengthier time periods than our experiments." (PMID 38976757, 2024). "This study links both processes by showing that cytidine deaminase APOBEC3A, a source of cancer-initiating mutations, also contributes to cancer progression by promoting ribosome biogenesis." (PMID 38976757, 2024). "APOBEC3s are major mutagenic drivers in cancer, and APOBEC3A and APOBEC3B are likely the most significant mutators among the APOBEC3 superfamily." (PMID 36978147, 2023). "While several studies have assessed the potential association between the APOBEC3A/B deletion variant and cancer development, the results are conflicting." (PMID 36394079, 2023). "APOBEC mutations have been linked to certain human cancer genomes, and the APOBEC3A/B deletion polymorphism has been associated with a higher risk of some cancers, including PCa." (PMID 37568712, 2023). "RNA-seq analysis showed that ectopic expression of APOBEC3A inhibited several cancer-associated signaling pathways." (PMID 38021159, 2023). "Further implicating APOBEC3A as a predominant mutator, an APOBEC3B germline deletion that generates a chimera of the APOBEC3A coding region fused to the 5′ UTR of APOBEC3B has been associated with more APOBEC-induced mutations in some cancers." (PMID 36978147, 2023). "According to previous studies, SPRR3 can stimulate cell proliferation, whereas APOBEC3A can cause virus evolution and cancer mutagenesis by mediating the antiviral response, exerting a ‘second‐hit’‐like effect to accelerate disease escalation." (PMID 36967539, 2023). "Cytidine deaminases activity causes instability and cancer in the human genome, and apolipoprotein B mRNA editing enzyme catalytic subunit 3A (APOBEC3A) is by far the most active member of this family." (PMID 36497451, 2022). "Taken together, these results indicate that APOBEC3B loss can increase APOBEC3A protein levels, activity and mutagenesis in some cancer cells." (PMID 35859169, 2022). "There is accumulating evidence that APOBEC3A and 3H are equally or even more potent mutators in cancers than APOBEC3B." (PMID 36970060, 2022). "Endogenous APOBEC3 deaminases generate prevalent mutational signatures in human cancer cells, and APOBEC3A is the main driver of these mutations." (PMID 35859169, 2022). "The frequency of the APOBEC signature in cancers is second only to the ageing signature and the majority of APOBEC-induced mutations in human cancers have been attributed to either APOBEC3A (A3A) or 3B (A3B) expression." (PMID 34197599, 2021). "Although the APOBEC3A induced mutations are common in cancers, APOBEC3A is often expressed with extremely low abundance." (PMID 34880864, 2021). "While APOBEC3A-induced mutations are common, APOBEC3A expression is rarely detected in cancer cells." (PMID 34389714, 2021). "The cytidine deaminase, APOBEC3A (A3A), is a prominent source of mutations in multiple cancer types." (PMID 34697369, 2021).
cancer (continued). "Our findings suggest that, in almost all investigated cancer types, germline APOBEC3A/B deletion was significantly associated with decreased expression levels of uc003awn and uc003awo, but there was an increased expression level of uc011aoc." (PMID 31533728, 2019). "Significant associations with decreased expression levels of uc003awn (APOBEC3A) were also observed in three cancer types – bladder, breast and thyroid." (PMID 31533728, 2019). "The AID and APOBEC3A mutable motifs are the most prominent features of the C:G>T:A transitions that constitute the vast majority of somatic mutations in studied cancers." (PMID 30759888, 2019). "Our analysis of cancer cell line data identified associations of drug sensitivity with expression levels of APOBEC3A, APOBEC3B, REV1, and UNG genes and with abundance of sequence motifs and kataegis clusters attributed to APOBEC activity." (PMID 29642934, 2018). "Leading candidates to account for the overall APOBEC mutation signature in cancer are APOBEC3A (A3A) and APOBEC3B (A3B)." (PMID 27650891, 2016). "It is unclear how APOBEC3A and 3B gain access to single stranded DNA leading to the singlet isolated mutations highly prevalent in mutated cancer genomes that bear the APOBEC signature." (PMID 25237741, 2014). "Additionally, APOBEC enzymes, particularly APOBEC3A, have been implicated in cancer progression by inducing mutations that drive genome instability and tumor heterogeneity." (PMID 40918643, 2025). "Furthermore, APOBEC3A contributes to the development of resistance to cancer therapies by accelerating mutational processes that enhance the adaptive potential of cancer cells, particularly in cases of relapse after treatment." (PMID 40021759, 2025). "In the groups of 50‐ to 59‐ and 60‐ to 69‐year‐old individuals the APOBEC3A/B deletion was associated with a significantly reduced cancer risk (dominant model: OR = 0.51; 95% CI = 0.33–0.78; p = 0.002 and OR = 0.62; 95% CI = 0.43–0.88; p = 0.008, respectively)." (PMID 36394079, 2023). "APOBEC3A mutates its host DNA in human cancers to evolve drug resistance." (PMID 37821454, 2023). "Notably, numerous tumor types have been assessed for the potential association between the APOBEC3A/B deletion variant and cancer risk." (PMID 36394079, 2023). "These inhibitors may be useful probes for studying APOBEC3A activity in cellular systems and leading toward, potentially as conjuvants, next-generation, combinatorial anti-mutator and anti-cancer therapies." (PMID 37821454, 2023). "Furthermore, Apobec3A has been proposed to play a crucial role in oncogenesis, as Apobec3A-induced mutations are increased in different cancer types." (PMID 37154747, 2023). "Direct identification of APOBEC3A as a major generator of prevalent mutational signatures in cancer is a critical step forward for future studies seeking to define the underlying causes of APOBEC3 mutagenesis and to take advantage of APOBEC3 mutagenesis for therapeutic benefit." (PMID 35859169, 2022). "Overexpression of APOBEC3A/3G/3H may lead to DNA fragmentation and increase genomic instability, which may lead to cancer risk." (PMID 36339709, 2022). "Thus, high expression levels and deaminase activity seemingly implicate APOBEC3B as the major mutator in all of the cancer cell lines analysed here, whereas analyses of extended sequence contexts and RNA-editing assays suggest a potential role for APOBEC3A." (PMID 35859169, 2022). "Given the link to specific mutational processes, several studies have assessed whether the APOBEC3A/B deletion variant may confer cancer risk." (PMID 34873230, 2021). "APOBEC3A (A3A) cytosine deaminase activity causes DNA damage and drives cancer mutagenesis." (PMID 33788831, 2021). "APOBEC mutational activity in cancer can be sustained by two main isoforms: APOBEC3A and APOBEC3B." (PMID 32317634, 2020). "Importantly, we demonstrate that the RNA mutation-based APOBEC3A assay is applicable to clinical samples from cancer patients." (PMID 32532990, 2020).
cancer (continued). "However, the influence of APOBEC-mutational signature and germline APOBEC3A/B deletion on neoantigens and TILs remains largely unexplored, especially in pan-cancer studies." (PMID 31533728, 2019). "APOBEC3A/B-induced mutations were described for many cancer types in previous study." (PMID 31200452, 2019). "In cancers that develop under conditions of chronic inflammation, deamination-associated C>T mutations are induced massively in association with expression of deaminase APOBEC3A and B." (PMID 30417129, 2018). "Their results suggested that the APOBEC3A/3B germline deletion allele confers cancer susceptibility through increased activity of APOBEC-dependent mutational processes, although the mechanism by which this occurs remains unknown." (PMID 27602762, 2016). "As chronic inflammation underlies many diseases including numerous cancers, it is possible that APOBEC3A induction may generate many of the lesions typical of a cancer genome." (PMID 23977391, 2013). "Thus, the association of APOBEC3A/B genotypes with cancer development remains controversial." (PMID 36980505, 2023). "Thus, mtdsRNA dysregulation may induce APOBEC3A and contribute to observed genomic instability and mutation signatures in cancer." (PMID 37474103, 2023). "Also, APOBEC3A expression was reported to cause DNA damage responses of cancers." (PMID 34745121, 2021). "Much less is known about the potential contribution of APOBEC3A-catalyzed RNA editing to virus and cancer evolution." (PMID 41727079, 2026). "The knowledge of DNA deamination motifs preferred by individual APOBECs revealed APOBEC3A as a major source of hypermutation in cancer." (PMID 41726872, 2026). "Collectively, our findings identify TMEJ as the preferred mechanism for repairing APOBEC3A-induced DSBs and establish Polθ inhibition as a novel promising strategy to eliminate cancer cells with APOBEC3A activity." (PMID 41278855, 2025). "In this study, we investigate how cancer cells withstand potentially lethal damage from APOBEC3A-induced DSBs." (PMID 41278855, 2025). "Over the past 10 years, numerous studies have linked the mutagenic activities of APOBEC3A and APOBEC3B to the generation of mutational signatures observed in over 50% of human cancers." (PMID 40143363, 2025). "Two APOBEC DNA cytosine deaminase enzymes, APOBEC3A and APOBEC3B, generate somatic mutations in cancer, thereby driving tumour development and drug resistance." (PMID 39548236, 2025). "The induced hyper-mutations of long stretches of single-strand DNA (ssDNA) formed during BIR (with APOBEC3A and APOBEC3B being the major mutators) through deamination, foster genome instability in cancer cells, a phenomenon referred to as ‘Kataegis’." (PMID 39910169, 2025). "This creates therapeutic vulnerability by depending on Polθ, the key TMEJ polymerase, thereby establishing Polθ inhibition as a rational synthetic lethal strategy for APOBEC3A-active cancers." (PMID 41278855, 2025). "APOBEC3A and APOBEC3B encode DNA editing enzymes with anti-viral roles that generate somatic mutations in cancer." (PMID 39548236, 2025). "This mutation signature has previously been identified in multiple cancer types as the mutational hallmark of APOBEC family cytidine deaminases, including APOBEC3A, a core component of BEACON224." (PMID 40449999, 2025). "Together, this study presents a promising therapeutic avenue to exploit vulnerabilities arising from APOBEC3A-induced DSBs to target cancer cells to counter tumor evolution and therapy resistance in the clinic." (PMID 41278855, 2025). "Similar to its increased expression resulting in off-target genomic DNA editing, APOBEC3A has been shown to edit mRNAs when expressed in cancer and this is possibly true for other APOBEC3 family members as well." (PMID 38976757, 2024). "Here, we provide compelling evidence that APOBEC3A regulates ribosome biogenesis in human cells, another distinct pathway that drives cancer." (PMID 38976757, 2024).
cancer (continued). "We identified a significant increase in APOBEC3A/B expression in cancer compared to precancers and controls." (PMID 39672307, 2024). "Two APOBEC (apolipoprotein-B mRNA editing enzyme catalytic polypeptide-like) DNA cytosine deaminase enzymes (APOBEC3A and APOBEC3B) generate somatic mutations in cancer, driving tumour development and drug resistance." (PMID 38496447, 2024). "Tumor genome sequencing has demonstrated that mutagenesis from APOBEC3A is widespread throughout human cancers, however the mechanisms that enable the dysregulated activity of APOBEC3A in cancer remain elusive." (PMID 38886582, 2024). "To date, APOBEC3A is emerging as the more prominent cytidine deaminase that edits the genome in cancer." (PMID 38976757, 2024). "This study defines a novel role of the SMC5/6 complex in maintaining genomic stability and viability of cancer cells in which APOBEC3A is active, revealing a potential therapeutic vulnerability." (PMID 38886582, 2024). "Cancer cells depleted of SMC5/6 incur substantial genome damage from APOBEC3A activity during DNA replication." (PMID 38886582, 2024). "Because the MCF10A cell line is not a cancer cell line, HeLa cells provide us with a more direct test of APOBEC3A’s role in a cancer context." (PMID 38976757, 2024). "Currently, cytidine deaminase inhibitors are being developed, including against APOBEC3A, with a focus on their application in cancer therapy." (PMID 38976757, 2024). "Together, our study provides evidence that APOBEC3A and APOBEC3B can generate distinct mutation landscapes in cancer genomes, driven by their unique substrate selectivity." (PMID 38499542, 2024). "Antiviral DNA cytosine deaminases APOBEC3A and APOBEC3B are major sources of mutations in cancer by catalyzing cytosine-to-uracil deamination." (PMID 38499542, 2024). "Even so, APOBEC3A’s newfound function in ribosome biogenesis emphasizes it as a top candidate cytidine deaminase target for cancer therapeutics." (PMID 38976757, 2024). "More broadly, we found an additional function of APOBEC3A in cancer pathology through its function in ribosome biogenesis, expanding its relevance as a target for cancer therapeutics." (PMID 38976757, 2024). "To evaluate the interaction of APOBEC3A activity and SMC5/6 loss in human cancers, we quantified APOBEC3A mutational signatures in tumors with deleterious mutations in SMC5/6 subunit genes." (PMID 38886582, 2024). "In cancer, the genotoxic potential of APOBEC3A activity can be exploited by inhibition of the essential DNA damage responses which it activates." (PMID 38886582, 2024). "This study provides evidence that APOBEC3A and APOBEC3B can generate distinct mutation landscapes in cancer genomes, driven by their substrate selectivity." (PMID 38499542, 2024). "Our results point towards the possibility that APOBEC3A is a direct and indirect modulator of ribosome synthesis, linking its expression to cancer cell proliferation through a novel mechanism." (PMID 38976757, 2024). "Last, we studied WGS data from cancer cell lines with APOBEC3A or APOBEC3B knockout (KO) experiments." (PMID 37922356, 2023). "A common 30 kb deletion affecting the APOBEC3A and APOBEC3B genes has been linked to increased APOBEC activity and APOBEC‐related mutational signatures in human cancers." (PMID 36394079, 2023). "RNA-seq indicated that most genes were downregulated, and several cancer-related signaling pathways were inhibited when APOBEC3A was upregulated." (PMID 38021159, 2023). "The deamination activities of most APOBEC3 proteins (including 3F) have been mainly investigated in the context of HIV infection, whereas APOBEC3A has been intensely studied for its role as a mutagen in cancer genomes." (PMID 36920219, 2023). "The cytidine deaminases APOBEC3A (A3A) and APOBEC3B (A3B) are prominent mutators of human cancer genomes." (PMID 37532520, 2023). "The APOBEC3A-mediated DNA damage exceeds the cellular tolerance, which promoting cancer cell apoptosis." (PMID 38021159, 2023).